CD4 (CD4 molecule)
Diseases named in the same sentence as CD4 in open-access papers (continued):
Sharing a sentence is not in itself a finding about the gene and the disease.
infection (continued). "However, a dramatic difference between LAI and LAINefdd infections was noted in the levels of CD4+CD8+ thymocytes present in the implanted human thymus." (PMID 22640559, 2012). "Activation of CD4+ T cells is also associated with upregulation of CCR5 and may therefore render T cells more susceptible to infection." (PMID 22675567, 2012). "During infection with L. monocytogenes a CD4 and CD8 T cell response is directed to LLO." (PMID 22403645, 2012). "Therefore, infection with a low dose of nef-deleted virus results in delayed replication and most strikingly a minimal capacity to induce peripheral CD4+ T cell depletion." (PMID 22640559, 2012). "Since the mucosal surfaces are a virtually serum-free environment, and several proteins present in bovine serum are known to inactivate α-defensins we first focused on optimizing the culture conditions for infection of primary human CD4+ T cells in serum-free medium." (PMID 23028850, 2012). "Thus, the continued accumulation of SseJ-specific CD4 T cells at later time points after infection required bacterial persistence." (PMID 22275869, 2012). "Accordingly, transfection of a Siglec-1 expression vector into Raji cells significantly increased their capacity for HIV-1 trans-infection to a reporter CD4+ cell line, and this effect was again abolished by pre-incubation of transfected cells with the mAb 7D2 (p<0.0001)." (PMID 23271952, 2012). "Granulomas in both primary and secondary infection consist of neutrophils, macrophages, dendritic cells, and eosinophils; in secondary infection, CD4+ Th2 cells and a high proportion of alternatively activated macrophages rapidly migrate to the site of infection to surround the larvae." (PMID 23053394, 2012). "The partial depletion of CD4+CD25+Foxp3+ cells by anti-CD25 treatment could, at least in part, explain the low numbers of CD4+CD25+ cells detected in the lungs of the A/J mice at week 2 of infection." (PMID 23226464, 2012). "Treatment of rejection with cytolytic agents such as thymoglobulin may result in prolonged depression of CD4 counts and significant infection-related morbidity." (PMID 22654630, 2012). "It has becomes increasingly evident that cortical actin presents itself both as a barrier to viral intracellular migration and as a necessary cofactor that the virus must actively engage, particularly, in the infection of resting CD4 blood T cells, the primary targets of HIV-1." (PMID 22640593, 2012). "The BT group showed a decrease in the percentage of cells CD4+IL-10+ at day 7 after infection, however higher levels of IL-10+ T-cells were seen in both groups, but this level increased at day 28 in MT group, an effects seen this increase occurred earlier at day 14 in the BT group." (PMID 22412949, 2012). "In addition, we demonstrate that CD4 T cell responses to infection of the respiratory tract are substantially modulated by the type of infecting virus in a manner that is host-dependent and reflects changes in the early induction of innate factors." (PMID 22457834, 2012). "For P0 SIV 239 CEMX174, sCD4 strongly enhanced infection (as did the CD4 blocking mAbLeu 3a)." (PMID 22830620, 2012). "In this assay, memory CD4+ T cells are generated from naive T cells by antibody and cytokine treatment and then infected with a luciferase encoding HIV-1 variant that undergoes a single cycle of infection." (PMID 22853692, 2012). "Progressive infection results in loss of CD127+132− and gains in CD127−132+ CD4+ and CD8+ T-cells." (PMID 22348045, 2012). "Blunted acute viremias might conceivably reduce gut CD4 T cell depletion, favor early restoration of mucosal T cells in the gut, and attenuate the course of infection." (PMID 22571771, 2012). "Besides the total virus population and the dynamics of the CD4+ T-cell infection rate, Schenzle includes target cells, infected cells and anti-viral activity in his model." (PMID 23202449, 2012).
infection (continued). "For example, the control of infection with protozoan parasite Leishmania major has been attributed to IL-12-mediated differentiation and expansion of CD4+ Th1 cells with subsequent IFN-γ secretion, activation of infected macrophages, and NO-mediated killing of parasite." (PMID 22481964, 2012). "In BDV-infection of mice and rats, the invasion of immune cells into the CNS is regularly accompanied by glial cell activation, up-regulation of proinflammatory cytokines and CD4+ and CD8+ T-cells play a crucial role in this process." (PMID 22848506, 2012). "While the earliest stages of mucosal transmission of HIV-1 have not been directly observed in human and are not fully understood, animal experiments suggest that CD4 T-cells are probably the principal cell type infected at the portal of entry and throughout the earliest stages of infection." (PMID 22808148, 2012). "Moreover, the CD4+ T-cell population is lost through infection by a virus particle at a rate of c ̃, and so the term c ̃⊗v ̃ models the rate that free viruses destroy CD4+ T-cells." (PMID 22536298, 2012). "The two types of donor CD4+ T cells provided significant, suboptimal and, importantly, comparable protection in B6.A-Fv2s hosts, at the peak of FV replication and expansion of infected erythroid precursors on day 7 post infection in this strain." (PMID 22589728, 2012). "In addition to DC-mediated HIV-1 trans-infection, long-term viral transfer to CD4+ T cells by DCs depends on HIV-1 production from infected DCs." (PMID 22479639, 2012). "Furthermore, transduction of a SIGLEC1-specific shRNA, but not of a control shRNA, decreased LPS mDC capacity for HIV-1 trans-infection to a reporter CD4+ cell line." (PMID 23271952, 2012). "A multispecific, strong, sustained, CD4+-T-cell-specific Th1 response may be seen in infections with HCV infection evolving to resolution." (PMID 22611419, 2012). "Inhibiting the migration of HIV-1-infected iDCs, may limit the dissemination of HIV-1 throughout the host, and the infection of target CD4+ T cells." (PMID 23119100, 2012). "Moreover, there was a significant expansion of peptide specific CD4+ IFN-γ producing cells at the site of infection (dLN)." (PMID 22470440, 2012). "We explored this using adoptively transferred CD4+ T cells isolated from pulmonary lymph nodes from wt versus lac1Δ-infected mice and evaluated whether their transfer affected the course of infection with the wt strain." (PMID 23110112, 2012). "Regardless of whether the assays are performed in sensitive or resistant mouse strains, both IL-12 and IFN-γ are produced ex vivo during secondary stimulation of cultured spleen and CD4+ T cells with Brucella antigens during the 1st week of infection." (PMID 22500859, 2012). "However, at lower levels of infection a substantial proportion of SIV DNA in resting CD4+ T cells is laid down early (when virus is still WT at the CTL epitope) and this WT reservoir persists at stable high levels during chronic infection." (PMID 22496643, 2012). "Infection of primary, resting CD4+ T cells induced fusion in approximately 4% of cells." (PMID 22448282, 2012). "Indeed, we observed that the increase in sCD4 sensitivity of the evolving R5 viruses correlates with the ability of their Envs to bind CD4 more efficiently as well as to mediate infection of cell targets that express low levels of the receptor." (PMID 23237529, 2012). "These cells nearly trebled in frequency among CD44hi CD4 T cells following infection (R3)." (PMID 22496920, 2012). "The abundance of costimulatory signals could also cooperate to inactivate Treg cells and consequently enlarge the spectrum of CD4+ T cell specificities involved in the early response to infection." (PMID 22272258, 2012). "It has been shown that HIV-1 severely depletes CD4+ T-cells in ex vivo infected human lymphoid tissue, with a depletion of 77 and 97% of CD4+ T-cells relative to uninfected samples after 8 and 13 days post-infection, respectively." (PMID 22616002, 2012).
infection (continued). "We considered the possibility that longer courses of sustained infection may result in substantial CD4+ T cell depletion." (PMID 22640559, 2012). "Additionally, we identified a relation between BSSL genotype and CD4 cell counts prior to infection." (PMID 22412885, 2012). "However, work examining the cellular source of IFN-γ following infection with LVS has suggested that CD4+ cells are the cell type primarily responsible for producing this cytokine at later time points in infection." (PMID 22428026, 2012). "Thus, it appears that infection with HCMV can lead to a change in a population of the CD4+ T-cells, making them capable of expressing NKG2D." (PMID 22870231, 2012). "Moreover, the number of dying cells in infected individuals greatly exceeds the number of HIV-infected cells due to detrimental effects of immune activation, HIV proteins or abortive infection on the bystander uninfected CD4 T cell population." (PMID 22312424, 2012). "The initial Trojan horse hypothesis suggested that HIV-1 capture by iDCs in the mucosa may protect the virus from degradation and allow its transport to secondary lymphoid organs, facilitating trans-infection of CD4+ T cells and fueling viral spread." (PMID 22545022, 2012). "Whether CD8+ T-cells colocalize in excess with CCR6+CD4+ T-cells for an efficient control of HIV replication in SP subjects during the first years of infection or in HIV-exposed uninfected individuals remains to be determined." (PMID 22470433, 2012). "Attachment of Env gp120 to CD4 on the target cell initiates infection." (PMID 22833745, 2012). "Mean CD4+ T cells per unit area were severely depressed during early infection." (PMID 22319447, 2012). "As previously shown, high-avidity F-MLV env122-141L-specific Vα2 CD4+ T cells are a minority subset in the naïve repertoire and only dominate the immune response to FV as a result of their preferential expansion during infection." (PMID 22589728, 2012). "However our data are in contrast to a report showing that CD11c-depletion during established infection with S. mansoni resulted in a significant reduction in IFNγ+ production by CD4+ T cells after ablation of CD11c-expressing cells." (PMID 22911108, 2012). "Taken together, these observations suggest that interventions aimed at preventing or reducing the immunologic damage caused by HIV-1 would be most effective if implemented during the earliest stages of infection, before the pool of memory CD4+ T cells becomes irreversibly compromised." (PMID 22511868, 2012). "However, concerning the CD4+ T lymphocytes, one can observe that the level is maintained throughout the infection." (PMID 22359669, 2012). "HIV preferentially establishes productive infection in activated CD4+ T cells." (PMID 23029309, 2012). "However, the early CD4+ T cell-dependent burst of IFN-γ production seems to be critical for the effective control of infection." (PMID 22811737, 2012). "We also evaluated the expression of CD69 by B220+ B and CD4+ T cells after infection with LP-BM5." (PMID 22691411, 2012). "It has been reported that a cathepsin inhibitor CA-074Me more significantly enhances CD4-independent HIV infection than CD4-dependent infection, and cathepsin protease activity in host cells is reverse-correlated with cellular susceptibility to the CD4-independent HIV infection." (PMID 23304142, 2012). "Indeed, it has been suggested that an active infection process requires clustering of multiple gp120 with multiple CD4 and coreceptors." (PMID 22640593, 2012). "This may render them extremely permissive to infection and may explain why some of the SP subjects begin loosing their CD4 counts, especially after many years of infection in the absence of ART." (PMID 22470433, 2012).
infection (continued). "The results of this study show that the virus-mediated killing of primary CD4+ T cells in the SupT1/PBMC cocultures was significantly delayed, suggesting that the preferential infection of SupT1 cells can induce the virus to spare primary CD4+ T cells from infection and depletion." (PMID 22701517, 2012). "Of these, 158 completed their month 12 follow up visit and fulfilled the criteria for long term infection based on the presence of any of the following: CD4 count <350 cells/mL, WHO stage≥II or first positive HIV serology more than six months ago and as described in the method section." (PMID 22905148, 2012). "Similarly, infection of CD4−/− mice with T. gondii results in protective acute CD8 T cell responses, but CD4 T cells are required to sustain immunity." (PMID 22912696, 2012). "Activated CD4+ T cells exhibit a value of 60 cells/μL throughout the course of infection." (PMID 22866173, 2012). "Therefore, we analyzed a subset of individuals (n = 66) for whom longitudinal CD4+ T cells counts for at least one-year post-infection are available." (PMID 23209412, 2012). "In many cases, the HRs essentially shifted when assumptions changed: e.g., the effect of CD4 being >200 cells/mm3 changed for HPV16/16-like infection from 1.68 to 1.86, and from 2.53 to 3.07 (still remaining significant) when 365 days were used in assumptions #2 and #3 instead of 450 days." (PMID 22292027, 2012). "Productive infection of CD4 T cells results in cytopathic effects and cell destruction." (PMID 22654630, 2012). "Le taux de lymphocytes CD4 constitue un facteur pronostic de l'infection par le VIH." (PMID 23133707, 2012). "Therefore, for further analysis, we evaluated HIV-1 tissue infection by enumerating CD4 T cells positive for intracellular p24 by flow cytometry." (PMID 23236398, 2012). "Importantly, infection intensity positively correlated with CD200R expression by CD4 T cells in individuals endemically exposed to schistosomal Ag." (PMID 22496920, 2012). "In addition, our study reveals that the BSSL HH genotype correlates with high CD4 cell numbers prior to infection." (PMID 22412885, 2012). "HIV-1 capture by mDCs has been shown to promote trans-infection of CD4+ T cells and other target cells, and we therefore analyzed whether sialyllactose recognition by mDCs is also important for viral transmission." (PMID 22545022, 2012). "Furthermore, mice that lack either CD4+ or CD8+ T cells develop severe disease upon infection with mouse-adaptive EV71." (PMID 23251663, 2012). "It was observed that treatment with allicin during P. yoelii 17XL infection could enhance host innate and adaptive immunity evidenced by elevated numbers of macrophages and CD4+ T cells and cytokines." (PMID 22873687, 2012). "The three patient groups were similar regarding age, gender distribution and estimated time since infection, while CD4+ T cell counts were different at M0 and at set-point (M6) between all groups, and viremia levels differed significantly between RP and SP at all time points." (PMID 23056251, 2012). "We infected DCs and four days post infection we co-cultured them with autologous CD4 T cells." (PMID 22685410, 2012). "Thus, although negative selection reduced the size and cross-reactivity of the available FV-reactive naïve CD4+ T cell repertoire, it increased the overall avidity of the repertoire that responded to infection." (PMID 22589728, 2012). "Decline in CD4+ T cell percentage could already be seen at 25 days after infection and continued until 120 days postinfection (4 to 6 mice each timepoint)." (PMID 22675567, 2012). "To determine whether subtype C T/F viruses, which account for the great majority of new infections worldwide, utilize CD4 or CCR5 with enhanced efficiency, we tested both T/F and chronic Env constructs in pseudotyping assays." (PMID 22693444, 2012).
infection (continued). "Similarly, epithelial-derived MUC1 in breast milk, which contains multiple repeating LewisX motifs, has been implicated in preventing cell-free HIV-1 transmission to DC and infection of CD4+ T cells." (PMID 22952771, 2012). "The infection receptors of HIV are CD4 and one of chemokine receptors (CXCR4 or CCR5)." (PMID 23304142, 2012). "Furthermore, the initial small pool of infected CD4+cells observed at 6 h post infection is amplified 10-fold within 24–96 h." (PMID 22412886, 2012). "When comparing the HIV infected to the uninfected patients, the predictors of Acinetobacter colonisation/infection included younger age (p = 0.042), female gender (p = 0.028), CD4 count below 200 cells/ml (p = 0.037), an APACHE II score greater than 30 (p = 0.010), and MODS (p = 0.032);." (PMID 23300673, 2012). "While previous deterministic modelling of the X4 switch demonstrated that X4 emergence can in principle be accounted for by increased activation of naive CD4+ T cells at later stages of infection, in the present analysis we extend these results by modelling X4 emergence as a stochastic process." (PMID 22866173, 2012). "Several immune cell types, including tolerogenic DCs, myeloid suppressor cells, IL-10-producing CD4+ T cells, B cells and Foxp3+ T regulatory cells, have confirmed roles in the modulation and inhibition of inflammation in the context of infection." (PMID 22563306, 2012). "However, once dendritic cells (DCs) encounter danger signals at the site of infection and get fully maturated, differentiation, of naïve CD4+ T cells is driven effectively through antigen recognition, cytokine milieu, and costimulation by CD80 and CD86." (PMID 22481964, 2012). "Activated CD4+ T cell expression of both markers is increased from the beginning of infection." (PMID 22359669, 2012). "Furthermore, while CD4+Foxp3− T cells numbers were similar between the two groups of mice on day 8 post infection, CD8+ effector T cell populations were elevated in the lungs of mice treated with anti-IL-10R compared to control or IgG isotype-treated mice." (PMID 22393401, 2012). "Lastly, a reduced frequency of allogeneic CD4+ cells expressing α4β1 was detected following co-culture with lung DCs from B. pertussis-infected mice, suggesting a defect in DC imprinting in comparison to the other infection groups." (PMID 23300813, 2012). "Stable CMV-specific CD4+ T-cell responses have been associated with control of late CMV reactivation in transplant recpient; whereas CMV-specific CD8+ T-cells seem to be more important in primary infection and during early phases after transplantation." (PMID 23071829, 2012). "The enhanced expression of IL-21 in vivo, in the GALT early in infection might serve as a transient immune enhancing mechanism to restore the massively depleted CD4+ T and Th17 cell populations." (PMID 22511950, 2012). "Within this target-cell activation hypothesis, the predominance of R5 virus at early stages of the infection is thus attributable to the majority of activated CD4+ T cells at early stages expressing a memory phenotype." (PMID 22866173, 2012). "We did not observe loss of CD4+CD8+ thymocytes in LAINefdd infections despite virtually complete depletion of this same cell population by LAI." (PMID 22640559, 2012). "Given the chronicity of HIV-2 infection, the long duration of infection before these children became eligible for ART at the same CD4 count threshold as HIV-1 infected children might have contributed to the poor immunological recovery." (PMID 22770231, 2012). "A similar phenomenon has been described for CD4 T cells whereby severe infection is associated with the production of anergic rather than effector CD4 T cells." (PMID 22363665, 2012).